IL1B (interleukin 1 beta)
Diseases named in the same sentence as IL1B in open-access papers (continued):
Sharing a sentence is not in itself a finding about the gene and the disease.
Hypertension (continued). "Circumscribed neuroinflammation and IL-1β signaling hence seem to play an important role in the pathophysiological cascade of hypertensive brain damage and the further maintenance of hypertension." (PMID 25519173, 2014). "Treatment with 40 mg/kg 4HCH reduced systolic hypertension, serum IL-1β, and TNF-α levels and suppressed the activation of nuclear factor kappa-light-chain-enhancer of activated B cells (NF-κB) and renal injury." (PMID 25003119, 2014). "Recent evidence suggests that hypertension is an inflammatory condition where various PICs such as TNF, IL-6 and IL-1β, both centrally and peripherally, have been shown to play an important role in the pathogenesis of hypertension." (PMID 23691105, 2013). "IL-1b also significantly contributes to Ang II-induced hypertension and renal injury." (PMID 41184958, 2025). "Genetic knockout of IL-1b also protected mice from Ang II-induced hypertension." (PMID 41184958, 2025). "Research results suggest that IL-1β participates in the pathogenesis of various hypertension types, indicating that similar regulatory mechanisms may be involved in vascular dysfunction despite the different etiologies of the disease." (PMID 40572711, 2025). "In addition, adipose tissue secreted pro-inflammatory cytokines, including IL-6, IL-1β and TNF-α induce changes in blood lipid levels, therefore, causing changes in the cardiovascular system and leading to hypertension." (PMID 40433411, 2025). "The produced ROS leads to activation of the NLRP3 inflammasome, resulting in activation of caspase-1, cleavage of pro-IL-1β and pro-IL-18, and the production of active forms of IL-1β and IL-18, which increase the inflammatory response, fibrosis, and vascular remodeling in hypertension." (PMID 40227195, 2025). "Patients with high blood pressure had higher serum IL-1β levels, according to earlier observations." (PMID 40079000, 2025). "Chronic pericyte exposure to TNFα, IFN-γ, or IL-1β (e.g., during the longer course of hypertension) compromises pericyte function, leading to BBB disruption, which is mediated through the decrease of angiopoietin 1 or platelet-derived growth factor receptor β (PDGFRβ) and its signaling." (PMID 39495252, 2024). "Therefore, the increases in pro-inflammatory and inflammatory cytokines such as IL-1β, IL-6, and IL-8 in monocytes lead to systemic inflammation and worsen metabolic syndrome, including hypertension in SAS patients." (PMID 38276286, 2024). "However, during hypertension onset at 10 weeks and robust hypertension at 16 weeks, the inflammatory markers Tnf, Il1b, Ccr1, Ccr5, Ilrn, and Ltb4r are statistically significantly upregulated in the kidney of female SHR vs WKY control." (PMID 39514592, 2024). "Essential hypertension patients were also reported to have elevated levels of IL-1Ra, which potentially could antagonize the effects of IL-1β in these patients." (PMID 38256155, 2024). "In hypertension studies, baicalin reduced hypertension-induced inflammation (significant reduction in IL-1β and IL-6) by increasing the expression of tight-junction proteins that could maintain intestinal integrity." (PMID 37298268, 2023). "Given that macrophage infiltration-related inflammation has been shown to exacerbate hypertension and vascular dysfunction, we examined whether the pro-inflammatory macrophages were involved in the IL-1β secretion and the upregulation of CD38 in ECs." (PMID 37718359, 2023). "This study comprehensively evaluated the changes of inflammation caused by high-salt diet in rats from the aspects of inflammatory cytokines (TNF-α, IL-8, IL-1β, and IL-6) and hormones related to hypertension (NE, LEP, and Ang II), and Vascular and renal lesions were also examined." (PMID 36925479, 2023). "In addition, some studies have found that people with hypertension have elevated levels of circulating inflammatory cytokines, including IL-6, IL-1β, and TNF-α." (PMID 36937901, 2023).
Hypertension (continued). "Moreover, the positive correlation between IL-1β and mean blood pressure in patients with essential hypertension has been demonstrated." (PMID 37745103, 2023). "IL-1β is an “early-response” cytokine which is produced by macrophages and monocytes, promotes the release of IL-6 as consequence of oxidative stress, a cardinal process in the pathogenesis of hypertension." (PMID 36247461, 2022). "NLRP3 activation results in caspase-1 activation and subsequent secretion of IL-1β and IL-18, the plasma levels of which are consistently high in patients with hypertension." (PMID 36620210, 2022). "For instance, our group demonstrated that the increased expression of inflammasome genes, including the flagellin sensor Nod-like receptor (NLR) family caspase recruitment domain (CARD)-containing protein 4 (NLRC4) and IL-1β are strong predictors of hypertension and arterial stiffness." (PMID 36364734, 2022). "IL-1β levels were higher in hypertension and mediated vascular inflammation." (PMID 33532132, 2021). "This study links miR-150-5p to SMC contraction, IL-1β, and hypertension." (PMID 34445357, 2021). "Elevated activation levels of the key NLRP3 inflammasome priming factor, NF-κB, in tissue and inflammatory cells are persistent in hypertension and result in exaggerated levels of circulating and tissue IL-1β and IL-18 in patients with essential hypertension and in animal models of the disease." (PMID 33494430, 2021). "In summary, there is a growing amount of evidence to suggest that IL-1β is involved in the pathogenesis of various types of hypertension, indicating analogous regulatory mechanisms may be involved in vascular dysfunction despite the distinct initial causes." (PMID 34445357, 2021). "This new information can potentially improve our understanding of the molecular mechanisms involved in hypertension pathogenesis and foster the development of therapeutic solutions for hypertension-related diseases, furthermore, helping to establish IL-1β as a valid target for hypertension." (PMID 34445357, 2021). "Different studies revealed that polymorphisms in the IL-1β gene are associated with higher blood pressure in ethnic populations; however, the question still remains whether IL-1β and IL-18 are inflammatory markers or mediators of hypertension in humans." (PMID 33494430, 2021). "The studies reviewed here bring new insight into how IL-1β impacts the pathogenesis of hypertension and may yield promising avenues in exploring new targets for the treatment of various hypertension conditions." (PMID 34445357, 2021). "Clinical hypertension is related to kidney inflammation and increased circulating levels of IL-1β and IL-18, indicating that inflammasome activity may be involve in the blood pressure fluctuation and kidney injury." (PMID 34305953, 2021). "Interestingly, in this study, there was a strong association between the level of IL-1β and hypoxia-inducible factor-1a (HIF-1a) in the blood, which established a link between the hypoxia and the IL-1β pathway in hypertension." (PMID 34445357, 2021). "These contradicting results have given rise to the debate regarding whether inhibiting IL-1β is beneficial in treating hypertension and therefore needs to be further investigated." (PMID 34445357, 2021). "Given its proven positive effect on hypertension and cardiovascular health, it would be beneficial to study the effects of physical activity on the changes in exercise-related miRNAs that control the activity of IL-1β." (PMID 34445357, 2021). "In addition, another new avenue of research in this area is related to the regulation of IL-1β by non-coding RNAs (ncRNAs) in hypertension." (PMID 34445357, 2021). "CANTOS afforded the unique opportunity to test whether IL-1β inhibition reduced blood pressure, prevented the development of incident hypertension, or modified relationships between hypertension and cardiovascular events." (PMID 31884854, 2020).
Hypertension (continued). "Interestingly, Losartan, an angiotensin II receptor blocker used to treat hypertension, inhibits LPS/ATP-induced IL-1β secretion by suppressing NLRP3 inflammasome." (PMID 33664731, 2020). "CANTOS thus afforded the unique opportunity to test formally whether IL-1β inhibition reduces blood pressure, prevents the development of incident hypertension, or modifies relationships between hypertension and cardiovascular events." (PMID 31884854, 2020). "Inhibiting NF-κB activity reduced NLRP3 and IL-1β levels, thereby reducing hypertension." (PMID 33633569, 2020). "IL-1β is elevated in patients with high blood pressure and type 2 diabetes mellitus." (PMID 32596261, 2020). "Indeed, we found that ginseng intake decreased the levels of cytokines, including IL-1β, IL-6, and TNF-α, and factors associated with high blood pressure, including ACE activity and angiotensin II." (PMID 32727012, 2020). "According to univariate linear regression analysis, hypertension, heart failure, decreased eGFR, circulating EPCs (both CD34+KDR+ and CD34+KDR+CD133+ cells), and increased inflammatory biomarkers (hsCRP, IL-1β, and TMAO) were all significantly associated with lower FMD." (PMID 30862856, 2019). "Elevation of cytokines IL-1β was observed in experimental hypertension animals." (PMID 30906225, 2019). "In this model, it is speculated that CaSR activation in VSMCs increases cytosolic [Ca2+]i, which stimulates NLRP3 inflammasome activation and leads to IL-1β and IL-18 maturation during hypertensive aortic fibrosis." (PMID 30906225, 2019). "Interleukin-1 beta (IL-1β) levels are elevated in hypertension." (PMID 31223486, 2019). "In the present study, 12-week-old SHR exhibited higher expression of inflammatory factors including TNF-α, IL-1β, IL-6, and iNOS at both mRNA and protein levels, which could be aggravated with the progress of hypertension and attenuated by captopril treatment." (PMID 30183974, 2018). "In contrast, for the autonomic dysfunction phenotype, brainstem Il1b and kidney Adrb1 dynamics showed increases during the pre-hypertensive and hypertension-onset time frames, respectively, which could be related to the absence of Ren-mediated influence." (PMID 28732007, 2017). "As the majority of CHD patients in our study had hypertension and were taking angiotensin receptor blockers, these factors may also have partially influenced the IL-1β levels measured in this study." (PMID 26098632, 2015). "A substantial production of NO has been shown to be induced by inflammation, where inflammatory cytokines such as TNF-α, IL-1β, and interferon-γ stimulate iNOS activity and may be responsible for hypertension and insulin." (PMID 24441717, 2014). "Interestingly; T2DM patients with hypertension shows significantly decreased levels of IL-1β and caspase-1 (P value = 0.024, 0.028, resp)." (PMID 23762057, 2013). "Despite several reliable cross-sectional studies showing the connectionof IL-1β and IL-1rato hypertension, researchers have not yet conclusively linked theseproinflammatory markers to blood pressure in a longitudinal study." (PMID 19125204, 2008). "The pro-inflammatory cytokines, such as TNF-α, IL-1β, and IL-6, which have been extensively studied for their implication in the pathogenesis of heart failure, were not elevated in the heart tissue, most probably due to a short period of exposure to hypertension." (PMID 40422564, 2025). "Polymorphisms in the IL-1β, IL-6, and TNF-α genes have been associated with an increased risk and severity of CVD, particularly influencing factors such as ulceration, age of disease onset, and comorbid conditions like arterial hypertension and ischemic heart disease." (PMID 39857734, 2025). "The elevated salivary IL-1β concentrations we observed in hypertensive patients could indicate that locally synthesized IL-1β in periodontal tissues can enter the bloodstream, contribute to the systemic pro-inflammatory status, and play a role in the pathogenesis of hypertension." (PMID 40572711, 2025).
Hypertension (continued). "In male SHR, genes involved in inflammation, renin-angiotensin signaling, and sympathetic processes (Il1b, Agt, and adrenergic receptor subunits Adra1b and Adrb2) were differentially expressed across multiple organs and time points throughout the progression of hypertension." (PMID 39514592, 2024). "Interestingly, serum IL-1β levels were higher in patients with essential hypertension compared to patients with familial hypercholesterolemia and healthy controls and were positively correlated with blood pressure in the patients with essential hypertension only." (PMID 38256155, 2024). "Additionally, IL-1β also participates in the pathogenesis of hypertension." (PMID 36937865, 2023). "Contrary to the absence of a relationship between IL-1β and the risk for incident hypertension, the same meta-analysis of observational studies demonstrated that higher baseline IL-6 levels are associated with a significant increase in the risk for incident hypertension by 51%." (PMID 36835838, 2023). "Thus collectively, IL-1β plays a crucial role in the progression of essential hypertension and may be a novel promising therapeutic targets of hypertension." (PMID 36703963, 2022). "In addition to C-reactive protein and IL-6, TNF-α, IL-1β, IL-18, and CCL2 cytokine levels also appear to be increased in hypertension and may confer risk of developing the disease." (PMID 34698811, 2021). "The inflammatory process in hypertension is characterized by increased levels of local inflammatory cytokines such as IL-6, IL-1β, TNF-α, and ICAM-1, which are highly correlated with an increased risk for hypertension, and may be useful diagnostic tools for hypertension in the future." (PMID 33906674, 2021). "On the contrary, results from the Canakinumab Anti-Inflammatory Thrombosis Outcome Study (CANTOs) showed that IL-1β might not be linked to hypertension given that hypertension did not improve in patients given the IL-1β inhibitor Canakinumab." (PMID 34445357, 2021). "Therefore, the P2X7 receptor, as the upstream of IL-1β, may become a promising target for the treatment of hypertension in the future." (PMID 33995071, 2021). "Notably, IL-1β was highly correlative to the incidence of hypertension seen in ADPKD." (PMID 34445357, 2021). "While inhibition of IL-1β with canakinumab reduces cardiovascular event rates, these analyses suggest that the mechanisms underlying this benefit are not related to changes in blood pressure or incident hypertension." (PMID 31884854, 2020). "While inhibition of IL-1β with canakinumab reduced cardiovascular event rates, these analyses suggest that the mechanisms underlying this benefit are not related to changes in blood pressure or incident hypertension." (PMID 31884854, 2020). "In addition, baicalin treatment attenuated hypertension-associated intestinal hyperpermeability and decreased the serum levels of inflammatory indicators such as high-sensitivity C-reactive protein (hs-CRP), interleukin 1 beta, and IL-6 in the SHRs." (PMID 31719823, 2019). "Thus, the stimulated IL-1β signal might be established genetically and independently on hypertension." (PMID 23326018, 2012). "In the PE rat model, downregulation of GCLM and SNAP23 and upregulation of RHOT2 were significantly correlated with clinical phenotypes such as hypertension and proteinuria, as well as changes in placental inflammatory factor levels (TNF-α, IL-1β, IL-6)." (PMID 41953137, 2026). "By activating the renin-angiotensin system and generating ROS in the paraventricular nucleus, direct inhibition of IL-1β, the primary proinflammatory cytokine in the NLRP3 inflammasome pathway, in addition to blocking NF-κB, also reduces hypertension." (PMID 40079000, 2025). "Hypertension increases shear stress, damaging endothelial cells and triggering inflammation via cytokines (e.g., MCP-1, IL-1β, TNF-α)." (PMID 40230380, 2025).
Hypertension (continued). "Chronic inhibition of NF-κB activity in the PVN of salt-sensitive hypertensive rats delays the development of hypertension through reducing NLRP3 and IL-1β expression, as well as attenuating the activity of IKKβ and NAD(P)H oxidase." (PMID 40433411, 2025). "This study also highlights the importance of inflammasome activation in hypertension, with concurrent involvement of the NLRP3/IL-1β and TLR4/NF-κB pathways in promoting kidney injury and inflammation." (PMID 40433411, 2025). "Morinda officinalis oligosaccharides suppressed the secretion of IL-6, IL-1β, and TNFα in LPD-stimulated astrocytes and exerted antidepressant activity in hypertension rats." (PMID 40108901, 2025). "In the current study, macrophage depletion in established hypertension significantly reduced renal TNF⍺, TGF-β1, and IL-1β levels, suggesting that renal macrophages sustain hypertension by mediating inflammation." (PMID 41175639, 2025). "Further, pretreatment with TNF-⍺ and IL-1β in the PVN sensitized rats to developing sympathoexcitation and hypertension in response to a subpressor dose of ANG II." (PMID 39627570, 2025). "For example, hypertensive animals and human patients have increased levels of IL-1β, IL-6, IL-17, TNF-α, CCL-2, C-reactive protein, and adhesion molecules, while immunosuppression attenuates hypertension." (PMID 39513878, 2024). "Several pro-inflammatory/inflammatory markers, including IL-1β, IL-6, IL-8, IL-17, IL-23, interferon-γ, CXCL10, and TNF-α, were found to be elevated in SAS patients with hypertension." (PMID 38276286, 2024). "The objective of this study is to demonstrate that activation of microglial CB2 receptors can effectively reduce the levels of TNF-α, IL-1β, and IL-6 in the paraventricular nucleus (PVN) through inhibiting aerobic glycolysis, thereby relieving hypertension." (PMID 38540753, 2024). "Oyarce and Iturriaga discovered that the mRNA levels of IL-1β, IL-6, and TNF-α were increased in the NTS of rats with hypertension following 21 days of IH." (PMID 38276286, 2024). "IL-1β is mainly secreted by the mononuclear phagocyte system (MPS) and plays a pathophysiological role in hypertension." (PMID 38791032, 2024). "From these cytokines, IL-1β, TNF, IL-29, IFN-α2, IL-28, GM-CSF, IFN-β, IL-10 and IFN-γ exhibited increased level in patients with hypertension in the second outbreak in comparison to those from the first one." (PMID 36817433, 2023). "Hypertension induced the increase in TNF-α, IL-1β, and IL-6 levels in the brain and serum, and CUMS further increased the levels of these pro-inflammatory cytokines." (PMID 36765376, 2023). "Expression of IL-10, IL-8, IL-1β, IL-6, IL-4, TGFβ1, TNFα and GM-CSF significantly decreased in the CSWT group compared with the hypertension group." (PMID 36362064, 2022). "However, it remains unclear whether the pro-inflammatory state induced by IL-1β is necessarily a good indicator of resultant hypertension in PWH, especially since HIV-1 infection in human monocytes efficiently induce IL-1β expression and inflammasome activation." (PMID 36093171, 2022). "In mice with deoxycorticosterone acetate and saline (1K/DOCA/salt)-induced hypertension, the mRNA levels of NLRP3, ASC, pro-caspase-1 and pro-IL-1β were evaluated, as well as the protein expression of active caspase-1 and mature IL-1β." (PMID 34305953, 2021). "Ex vivo silencing of TIFA protein expression suppressed the secretion of IL-1β and TNF-α in PBMCs from patients with PAH or systemic hypertension." (PMID 34238983, 2021). "In the PPI network, we observed that IL-6, CCL2, IL-1β, MMP-2, and MMP-9 were the hub targets of GZD for improving hypertension." (PMID 33906674, 2021). "Inhibition of IL-1β can attenuate the overactivation of RAAS and decrease the overproduction of other pro-inflammatory cytokines, thereby improving hypertension and cardiac fibrosis." (PMID 33906674, 2021).